SOX4 (SRY-box transcription factor 4)
Diseases named in the same sentence as SOX4 in open-access papers (continued):
Sharing a sentence is not in itself a finding about the gene and the disease.
cancer (continued). "We attribute this effect principally to the ability of miR-335 to target the transcription factor SOX4, which is overexpressed in many different cancer types." (PMID 34945712, 2021). "In many cancers, abnormal expression of the key transcription factor SOX4 can induce EMT and accelerate cell proliferation." (PMID 34386303, 2021). "SOX4 interacts with multiple other transcription factors, rendering its impacts on gene expression and leading to the promotion of cell survival, cancer stemness, EMT and metastasis." (PMID 34055896, 2021). "A data analysis of human cancer transcription profiles found that SOX4 is one of 64 upregulated genes, which further indicates that SOX4 plays a role in many malignant tumors." (PMID 34863188, 2021). "First, several studies have reported that SOX4 inhibition by genetic manipulation suppresses the proliferation and metastasis of cancer cells in vitro and in vivo." (PMID 33482915, 2021). "On one hand, restoration of SOX4 expression increased invasiveness of cancer cells whereas this characteristic was decreased in SOX4 KO cells." (PMID 34768751, 2021). "Accumulating evidence indicates that SOX4 is an oncoprotein in numerous cancers including breast, liver, colorectal, and esophageal cancers." (PMID 33824274, 2021). "We also identified several genes previously linked to cancer progression, such as midkine (MDK), SOX4 and LYZ1,31." (PMID 34764257, 2021). "This study thus explores a novel mechanism that SOX4 promotes cancer stemness and suggests that HDAC1 inhibition would be an effective strategy for eradicating human CSCs driven by SOX4 overexpression." (PMID 33482915, 2021). "This showed a significant positive correlation of genes in cluster 3 with the genes that were co-expressed with SOX4 in human cancers." (PMID 34584219, 2021). "SOX4 is a key transcription factor involved in occurrence and development of many cancers and was shown to be related to the proliferation, migration, and invasion of GA cells and prognosis of GA patients." (PMID 34386038, 2021). "Phylogenetic tree analysis showed that the highly expressed SOX members in various cancers, i.e., SOX4, SOX11, and SOX12, were closely clustered, suggesting similarities in amino acid sequences among these three SOX members." (PMID 34442467, 2021). "In our study, we found amplification of SOX4 and their upregulated expression in multiple cancer types." (PMID 34442467, 2021). "While, despite the importance of SOX4 in cancer development, its role in stemness maintenance of human cancer has not been fully understood." (PMID 33482915, 2021). "Collectively, these results suggest that SOX4 is a key regulator of MM growth and survival as observed previously in carcinoma models." (PMID 34945712, 2021). "SOX4 gene has been reported to be frequently amplified and upregulated in over 20 types of malignant tumors." (PMID 33448691, 2020). "SOX4 plays important roles in the development of bone, islet and heart, and is related to osteoporosis, cancers, and other diseases." (PMID 33005101, 2020). "The up‐regulation of SOX2, SOX4, SOX5, SOX8, SOX9 and SOX18 are found to be associated with poor outcome in different cancer types; however, the up‐regulation of SOX11 and SOX30 is favourable for the prognosis in other cancer types." (PMID 32363730, 2020). "Some studies have reported that the principal role of SOX4 is related to the promotion of cancer cell proliferation." (PMID 32046103, 2020). "Previous studies have reported that SOX4 is highly expressed in over 20 malignant tumors and promotes malignant phenotypes." (PMID 33005101, 2020). "Evaluated SOX4 gene expression is observed in many cancer types, and increased SOX4 activity contributes to cellular transformation and metastasis." (PMID 32090981, 2020). "For example, SOX4 promotes cancer metastasis by inducing the epithelial–mesenchymal transition in acute myeloid leukemia, breast cancer, and prostate cancer." (PMID 30858360, 2019).
cancer (continued). "NR2F1-AS1 knockdown reduces cancer cell viability and metastasis and promotes apoptosis; these actions are mediated by the sponging of miR-363 and increased SOX4 expression, resulting in the activation of the PI3K–AKT–GSK-3β pathway." (PMID 31801112, 2019). "The poor survival samples also over-expressed CTNNB1 and SOX4 and under-expressed PIK3R1 and TP63, all of which have been linked to tumorigenesis in other cancers." (PMID 29484115, 2018). "Accordingly, SOX4 hypomorphic mice have decreased cancer-incidence and a resistance to carcinogen-induced skin cancer." (PMID 30507376, 2018). "In this study, we established that SOX4 is induced by Wnt signaling in number of human cancer cell lines of different entities." (PMID 29977599, 2018). "Predictably, the drug combinations cooperatively blocked constitutive and Wnt3a-induced SOX4 expressions in cancer cell lines, and this effect was rescued in DDIT3−/− cells." (PMID 29977599, 2018). "Two control mRNAs, CTNNB1 (β-catenin) and hTERT, which are constitutively expressed in cancer cells, were unaffected, suggesting that the effect on SOX4 mediated by iEVs-335 was specific." (PMID 30514916, 2018). "We conclude that expression of SOX4 is Wnt-inducible and sensitive to Metformin preferentially in cancer cells." (PMID 29977599, 2018). "SOX4 gene expression is upregulated in many cancer types, and increased SOX4 activity contributes to cellular transformation, cell survival, and metastasis." (PMID 30072631, 2018). "This relevance to cancer development, involvement in at least two major cancer cell signaling pathways ˗ Wnt and TGFβ ˗ makes SOX4 a good candidate to be used as a marker gene suitable for assessment of anticancer treatments." (PMID 29977599, 2018). "A systematic review and meta-analysis of SOX4 as a potential prognostic factor in human cancers was carried out analyzing the expression status of SOX4 in twenty kinds of human cancers at a protein level (The Human Protein Atlas)." (PMID 30072631, 2018). "A recent meta-analysis of available gene expression profiling data identified SOX4 as a member of a consensus gene expression ‘cancer signature’." (PMID 28632775, 2017). "One of the up-regulated genes was the sex-determining region Y (SRY) box 4 (SOX4), a transcription factor which is overexpressed in many types of human cancers." (PMID 28632775, 2017). "The functional involvement of Sox4 and Slug in miR-204-mediated cancer stemness and EMT was further clarified." (PMID 26933999, 2016). "A schematic representation of the EGCG-targeting Sox4 and Slug in the regulation of the cancer stemness and EMT resulting lymph node metastasis of OSCC cells is shown." (PMID 26933999, 2016). "Knockdown of miR-204 in OSCC cells enhanced cancer stemness and metastasis, while co-knockdown of Slug and Sox4 effectively reversed these phenomena." (PMID 26933999, 2016). "miR204-mediated inhibition of Sox4 and Slug consequently disrupted the maintenance of the cancer stemness and EMT properties of OSCC in vitro and in vivo." (PMID 26933999, 2016). "Some of them have been reported to be cancer-associated genes such as CDC25A, CDKN1A, MMP1, MMP13 and SOX4." (PMID 27863388, 2016). "Among identified piRNAs, Hsa_piR_017723_DQ594464 putatively targets FOS, a positive modulator of myeloid differentiation of hematopoietic progenitor; hsa_piR_020814_DQ598650 targets SOX4, an apoptosis regulator in different human cancers." (PMID 26760763, 2016). "In this report, our studies illustrated an novel-regulatory role of the miR-204-targeting Sox4 and Slug co-expression in the regulation of cancer stemness, EMT, and lymph node metastasis of OSCC cells." (PMID 26933999, 2016). "Taken together, these results suggested that SOX4 functions to modulate cancer proliferation by regulation of cell cycle, and inhibit cancer cell sensitivity to therapeutic drug via upregulation of ABCG2." (PMID 26583330, 2015).
cancer (continued). "The sex-determining region Y box 4 (Sox4) is a transcriptional factor, which preferentially regulates the development of various organs, tissues, and cancers." (PMID 25970172, 2015). "We detected its expression during cell cycle progression in CNE2 cells and found that SOX4 increased during the G1 to S phase, this confirmed the connection between SOX4 overexpression and cancer progression." (PMID 26578818, 2015). "Several target genes of miR-204, including HOXA10, MEIS1, FOXC1, MAP1LC3B, BCL2, NTRK2, SOX4 and EphB2, have been identified in different cancers." (PMID 26710269, 2015). "The resistance to cisplatin, a class of platinum-containing anti-cancer drugs that ultimately triggers apoptosis, was measured in SOX4-modified CaSki cells." (PMID 26583330, 2015). "SOX4 appears to have a context-dependent role in cancer as it is upregulated and promotes growth of leukemia, colorectal, lung and breast cancers, but is underexpressed and suppresses growth of bladder and liver cancers." (PMID 25594027, 2014). "An earlier study suggests that Ras also induces the expression of other EMT inducer such as Twist1 and SOX4 in cancer cells." (PMID 24721839, 2014). "We also identified many interesting genes regulated by SOX4, suggesting SOX4’s diverse roles in cancer cells." (PMID 25366337, 2014). "SOX4 was further identified as a common transcription factors for neoplastic transformation and progression in a large-scale meta-analysis of cancer microarray data." (PMID 25366337, 2014). "Despite its elevated expression in human cancers, the transcriptional changes mediated by SOX4 remain poorly defined." (PMID 23301048, 2013). "High levels of SOX4 mRNA expression are present in nearly all major human cancers and SOX4 has been recognized as one of the 64 cancer signature genes." (PMID 23301048, 2013). "SOX4 was the only individual marker which showed amplification at a significantly higher rate in Ta grade 3+T2 grade 2 cancers (11 of 61) than in Ta grade 1 or 1–2 cancers (0 of 23, p = 0.03)." (PMID 23593348, 2013). "Previous studies have shown that the oncogenic SOX4 transcription factor plays an important role in Wnt signaling pathways in many cancers including TNBC." (PMID 24188694, 2013). "Restoration of miR-129 in cancer cells by pharmacological induction of histone acetylation and DNA demethylation resulted in decreased SOX4 expression." (PMID 24194897, 2013). "Here, we have reported the neo-expression of SOX4 in both pancreatic precursor lesions and defined cancer." (PMID 23251334, 2012). "Through in vitro knocking out the expression of Sox4, the induction of apoptosis and growth suppression in cancer cells were demonstrated." (PMID 23443092, 2012). "SOX4 is overexpressed in many human malignancies, but the precise role of SOX4 in cancer progression is still not well understood." (PMID 22098624, 2011). "We found that SOX4 interacts with plakoglobin in a WNT3A-dependent manner in our experimental cancer model." (PMID 22098624, 2011). "For example, SOX4 is overexpressed in several cancers, such as bladder cancer, in which it is 5-fold upregulated compared with normal tissues." (PMID 22098624, 2011). "Subsequently, we wanted to investigate if the SOX4 transcripts observed in cancer were also translated into protein." (PMID 19156145, 2009). "The transcription factor SOX4 is known to be overexpressed in various cancers, including HCC, and may play a key role in these processes." (PMID 40399256, 2025). "LINC00963 was also reported to be significantly upregulated in cSCC lines as well as in several other cancers; in cSCC, it regulates cell proliferation and migration via miR-1193/SOX4 axis (suppressing miR-1193 expression and promoting SOX4 upregulation and tumoral progression)." (PMID 40725772, 2025).
cancer (continued). "In particular, SOX4 has been reported to be overexpressed in HNSCC and to be related to cancer progression and chemoradioresistance, so it might be worth investigating the relationship between miRNA-129-3p and SOX4 in HNSCC through further research." (PMID 39851970, 2025). "HOXB-AS1 may also act as a ceRNA to promote metastasis, upregulating the expression of the transcription factor SOX4 by competitively binding to certain miRNAs, which activates downstream genes involved in the acquisition of the hallmarks of cancer." (PMID 41440381, 2025). "Elevated expression of SOX4 has been associated with poor prognosis in several cancers, including colorectal, lung, breast, and notably, HCC." (PMID 40399256, 2025). "For example, SOX4 is considered a significant regulator of EMT in many cancers." (PMID 38164286, 2024). "In addition, SRY-Box Transcription Factor 4 (SOX4) is considered an important developmental transcription factor and an independent prognostic factor in human cancer, playing a crucial role in regulating EMT." (PMID 38800413, 2024). "Cheng and coworkers identified SOX4 as an atherosclerotic marker in mouse aortic tissues and distinct human arteries (human coronary arteries and human renal arteries), in addition to a cancer marker." (PMID 39518344, 2024). "SOX4 has been detected in several cancers including PAC, where it was reported in very few studies." (PMID 39118797, 2024). "MiRNA-19a-3p has been identified as a suppressor of invasion and metastasis in PC by inhibiting SRY-related high-mobility group box 4 (SOX4), a factor involved in the development, differentiation of cells and organs, as well as the initiation and progression of cancer." (PMID 38473877, 2024). "In the context of NSCLC, SOX4 also exerts a cancer-promoting effect that cannot be ignored." (PMID 39349443, 2024). "Sox4, one of the SoxC proteins in humans, is often amplified and overexpressed in multiple cancers, and Sox4 is known to play crucial roles in cancer development and progression, and has been classified as a “cancer signature” gene." (PMID 39005444, 2024). "The role of SOX4 in these cancers is still open to question and further discussion." (PMID 37958409, 2023). "SOX4 also plays an important role in tumorigenesis and cancer progression." (PMID 37958409, 2023). "Emerging researches show that miR-211 targets SOX4 to regulate cancer progression." (PMID 35912006, 2022). "Sry-related high-mobility group box 4 (SOX4) was proved to be a pro-cancer gene in ESCC." (PMID 35241028, 2022). "Key genes that contribute to gliogenesis but also contribute to the stemness in GBM: Notch (cancer stem cells), Sox9, Sox4, and SHH.Notch signaling pathway: In gliogenesis, Notch effector protein (NIFA) binds to GFAP promotor and contributes to astrocytogenesis." (PMID 35538578, 2022). "Besides, recent studies have also confirmed that STAT3 can participate in the cancer process by mediating the expression of Sox4." (PMID 35513871, 2022). "Treatment of MGH-CP1 does not induce p-AKT signal in mouse liver tissues, suggesting that the activation of PIK3C2B/SOX4/AKT might be tissue-specific or cancer cell line specific." (PMID 36347861, 2022). "Therefore, the αvβ6–TGFβ–SOX4 pathway is essential in conferring cancer cell resistance to T cell-mediated cytotoxicity and serves as a promising therapeutic target for cancers." (PMID 35267473, 2022). "Thus, our final purpose is to disclose the hsa_circ_0000277/miR-873-5p/SOX4/Wnt/β-Catenin axis in cancer progression and chemoresistance of ESCC." (PMID 35241028, 2022). "Evidence increasingly demonstrates that SOX4 act as an oncogene in several cancer progression." (PMID 35800365, 2022). "Also, previous studies found that SOX4 usually exerts a transcriptional regulation in the form of sequence-specific DNA binding during the development and progression of cancer." (PMID 36451857, 2022).
cancer (continued). "Sox4 could induce tumorigenesis by endowing cancer cells with survivability, mobility, and invasiveness." (PMID 35513871, 2022). "Taken together, PIK3C2B and SOX4 induction might confer resistance to TEAD inhibitors in cancer cell lines." (PMID 36347861, 2022). "Interestingly, although SOX4 acts as a transcription activator in most cancers, its transcriptional repression role has been found in two HCC cell lines." (PMID 35267473, 2022). "In summary, our results demonstrate that transcriptional activation of HDAC1 is the primary mechanism underlying SOX4 supporting cancer stemness and this finding suggests that inhibition of HDAC1 would be an effective therapeutic strategy for human cancer with aberrant SOX4 upregulation." (PMID 33482915, 2021). "Among the next genes, SOX4 is known to be highly expressed in a variety of cancers." (PMID 34235197, 2021). "Through literature reports, we found that SOX4 may exist as an inhibitory regulator of many cancers." (PMID 34863188, 2021). "The alteration frequency of SOX4 was determined in various types of cancers." (PMID 34442467, 2021). "In addition, SOX4 is overexpressed in many human malignant tumors, but the mechanism of SOX4 in cancer progression is unclear." (PMID 34863188, 2021). "Functional assays showed that overexpression of SOX4 could partially reverse the anti-cancer effects of miR-30d." (PMID 33824274, 2021). "First, we used the SingleR package and the known markers of cancer and alveolar cells to identify a cancer cluster and alveolar cluster; EPCAM and SOX4 were used to mark the cancer cluster; SFTPC and SFTPA1 to mark the alveolar cluster; CAPS and TPPP3 to mark epithelial cells." (PMID 33783985, 2021). "By proteomics study, we found that, in CRC spheres, SOX4 regulates several important signaling pathways involved in stemness maintenance for both normal and cancer stem cells, including Hippo signaling pathway, cell cycle, PPAR signaling pathway, and Notch signaling pathway, etc.." (PMID 33482915, 2021). "It has been reported that SOX4/ Wnt/β-catenin signaling contributes to cancer development." (PMID 34015763, 2021). "SOX4 is potentially important in the tumorigenesis of a number of different cancers, including NPC." (PMID 32586280, 2020). "Moreover, the effect of SOX4 on cancer cell resistance to chemotherapeutic agents was also evaluated in vitro and in vivo." (PMID 33005101, 2020). "Moreover, SOX4 was reported to be involved in many pathways that are commonly activated in various cancers, including PI3K/Akt signaling, Wnt signaling and MAPK signaling." (PMID 32552762, 2020). "In addition to regulating the differentiation of epidermal cells, SOX11 and SOX4 also control migration, in line with their reported role in migration in mesenchymal stem cells, neuronal cells, and a variety of cancer cells." (PMID 31492871, 2019). "SOX4 is a key transcription factor involved in development of several cancers." (PMID 30922402, 2019). "The positive rate of SOX4 expression was about 78% in overall cancer tissues." (PMID 30072631, 2018). "The study concluded that SOX4 is a potential prognostic biomarker in human cancers." (PMID 30072631, 2018). "Here we show that iEVs generated in B cells and enriched in miR-335 can be used to restore miR-335 endogenous content in triple negative cancer cells that have a reduced content, enabling the regulation of SOX4, a transcription factor that is overexpressed in cancer cells." (PMID 30514916, 2018). "Accumulating evidence has demonstrated that Sox4 is a key regulator in multiple cellular processes and down-regulation of SOX4 could inhibit cancer cells metastasis." (PMID 29490000, 2018). "It has been shown before that SOX4 also mediates TGFβ signaling during cancer progression." (PMID 29977599, 2018). "SOX4 is an important regulator of EMT functioning in cancer progression." (PMID 28038442, 2017). "Numerous studies have found SOX4 plays an oncogenic role in many kinds of human cancers." (PMID 28133610, 2017).